ATXN2 (ataxin 2)
Diseases named in the same sentence as ATXN2 in open-access papers (continued):
Sharing a sentence is not in itself a finding about the gene and the disease.
Parkinsonism (continued). "Ataxin-2 gene (ATX2) is linked to a number of neurodegenerative disorders in humans including ALS and Parkinson disease (PD)." (PMID 25414671, 2014). "Moreover, the finding that ATXN2-linked parkinsonism may be associated with an interrupted CAG repeat region, versus the pure CAG repeats typical of SCA2, raises the possibility that the CAG purity of the repeat expansion may contribute to disease manifestation." (PMID 21479228, 2011). "Neither the HTT gene nor the ATXN2 gene showed a significant predictive effect on cancer risk in patients with Parkinson’s disease." (PMID 39974178, 2025). "Future biochemical studies are needed to elucidate whether HTT, ATXN1 and ATXN2 CAG can trigger not only the Htt or ataxin aggregation but also other pathological proteins such as a-syn as well, and this explains their Parkinson’s disease genetic risk." (PMID 39974178, 2025). "Moreover, in addition to the genes mapped to the sequentially numbered PARK1-15 loci, other genes, such as MAPT, ATXN2, ATXN3, spatacsin, and POLG1, are known to cause syndromes that can clinically manifest with parkinsonism as one of the symptoms." (PMID 22623900, 2012). "However, similar length expansions that are interrupted with other codons, can present atypically with parkinsonism, suggesting that configuration of the repeat sequence plays an important role in disease manifestation in ATXN2 polyQ expansion diseases." (PMID 21479228, 2011). "Our ataxin-2 transgenic fly models express a pathogenic polyQ ataxin-2 protein encoded by different glutamine-coding codons: the SCA2-associated CAG repeat, interrupted CAA/G repeat associated with parkinsonism and ALS, or an experimentally produced pure CAA repeat." (PMID 34077532, 2021). "Based on this observation we postulated that ATXN2 intermediate alleles with 32–35 CAG may evolve from large ANs with 23–31 CAG, explaining familial or sporadic cases associated either with SCA2, ALS, and Parkinsonism." (PMID 23936447, 2013). "Interestingly, another study suggested intermediate alleles in ATXN2 as phenotypic modifiers in FTD, reporting a positive association between an intermediate number of CAG repeats and an earlier onset of the disease, Parkinsonism and psychotic symptoms at disease onset." (PMID 38397958, 2024). "Gender, AOga, AOfs, CAGexp at ATXN2, and presence/absence of amyotrophy, parkinsonism, dystonic manifestations and cognitive decline at baseline, were studied as potential modifier factor of disease progression according to both models (study duration model and disease duration model)." (PMID 29370806, 2018). "ATXN2 expansion explains most but not all variability in age at onset (AO) of symptoms, and it was related to presence of some neurological findings such as dystonic movements and parkinsonism." (PMID 29370806, 2018). "A case–control or cancer–non-cancer Parkinson’s disease comparisons were conducted to examine the size of the HTT, ATXN1 and ATXN2 CAG repeats in the different groups." (PMID 39974178, 2025). "A high frequency of 27Q repeats was noticed in ALS patients, Parkinson's disease (PD) patients, and controls in Europe and North America, but not in Chinese ALS patients or healthy controls, where the peak of 27 CAG repeats in the ATXN2 gene was essentially absent." (PMID 25148523, 2014).
frontotemporal dementia (32 papers, 2009 to 2026). Frontotemporal dementia (FTD) comprises a group of neurodegenerative disorders, characterized by progressive changes in behavior, executive dysfunction and language impairment, as a result of degeneration of the medial prefrontal and frontoinsular cortices. "Furthermore, ATXN2 plays a pathogenic role as a phenotypic modifier in frontotemporal lobar degeneration (FTLD), with associations observed between CAG repeat amplification in ATXN2 and the age of onset of FTLD, as well as the manifestation of Parkinson's syndrome and psychotic symptoms." (PMID 39039334, 2024). "It seems that the (GGGGCC)n hexanucleotide repeat expansion in the C9orf72 gene, plus the intermediate-length CAG expansion in the ATXN2 gene, potentiate the development of an ALS variant characterized by frontotemporal-dementia." (PMID 38877004, 2024). "In addition, ATXN2 patients exhibit more frequent spinal onset, concurrent frontotemporal dementia, and shorter survival up to 1 year." (PMID 40276954, 2025). "Another group also identified that ASOs targeting ataxin 2 could suppress neurodegeneration in ALS and frontotemporal dementia (FTD) mediated by a GGGGCC hexanucleotide repeat expansion in patient-derived neurons." (PMID 34054431, 2021). "However, changes in several other genes have been suggested as causes for recessive neurological/neurodegenerative disorders that may include PD: hereditary ataxias (ATXN2/3, FMR1), frontotemporal dementia (e.g. MAPT) and others (e.g. ATP13A2, PLA2G6, FBXO7)." (PMID 23976986, 2013). "Interestingly, ATXN2 also serves as a major modifier of ALS, with significant interactions observed between ATXN2 and pathologically expanded HRE-induced C9orf72 deletions, leading to ALS-frontotemporal dementia (ALS-FTD) pathogenesis." (PMID 39039334, 2024).
Obesity (21 papers, 2009 to 2025). Accumulation of substantial excess body fat. "Consistent with the apparent role of ATXN2 in regulating nutrient signaling and metabolism, ATXN2 polyQ expansion has been linked to obesity and type I diabetes." (PMID 28587229, 2017). "Genetic linkage studies of human obesity-related traits have also implicated the ATXN2 region on human chromosome 12q24." (PMID 20016785, 2009). "Previously, we reported that Atxn2-deficient mice developed obesity when fed a moderately fat-enriched diet (Purina mouse diet 5015: calories from protein 18.2%, fat 25.8%, and carbohydrates 55.9%)." (PMID 19617910, 2009). "ATXN2 dysfunction has also been linked to obesity and diabetes." (PMID 38877004, 2024). "Furthermore, the deletion of Atxn2 in mouse as well as single nucleotide polymorphisms at the chromosomal ATXN2 locus in human implicated ATXN2 in hepatosteatosis, obesity, dyslipidemia, insulin resistance, diabetes mellitus and arterial hypertension." (PMID 25721894, 2015). "Based on our finding of hyperphagia and obesity in mice hemizygously or homozygously deficient for ATXN2 we tested the hypothesis that loss-of-function mutations in ATXN2 are responsible for a subset of human obesity." (PMID 20016785, 2009). "We tested the hypothesis that rare loss-of-function ATXN2 variants cause obesity analogous to rare mutations in the leptin, leptin receptor and MC4R genes." (PMID 20016785, 2009). "Furthermore, ATXN2 gene variants could be important for other obesity-related phenotypes such as later-onset obesity or obesity associated with developmental delay." (PMID 20016785, 2009). "Recently, it was shown that overexpressing ATXN2 specifically in the hypothalamus prevented high-fat diet-induced obesity and insulin resistance." (PMID 38877004, 2024). "Altogether, the Atxn2-KO mice showed obesity and hepatosteatosis in contrast to the progressive loss of weight and fat stores in the Atxn2-CAG100-KIN mice." (PMID 31766565, 2019). "Conversely, increased A2BP1 expression was found in obesity, Also, this gene interacted with ATXN2, INSR, and MC4R, which played important roles in metabolic pathways." (PMID 30547318, 2019). "For example, Ataxin-2 is involved in embryonic development, apoptosis, actin development, cellular proliferation, insulin signaling in obesity, and various metabolic processes to name a few." (PMID 28587229, 2017). "The link between ATXN2, obesity and diabetes was corroborated by a later study in which Atxn2-KO mice also exhibited obesity and hepatosteatosis." (PMID 28587229, 2017). "Although the link between ATXN2 and obesity/diabetes is intriguing, research employing a larger cohort is needed in order to clarify the significance of these findings." (PMID 28587229, 2017). "A genetic ablation of the RNA-binding protein ATXN2 in mice leads to obesity, appearance of lipid droplets in the liver, increased blood cholesterol, cerebellar gangliosides, and sulfatides." (PMID 24659297, 2014). "The rationale for the present study was provided by the finding of obesity in Atxn2 knockout mice and the presence of linkage signals for obesity-related traits on 12q24, the location of the human ATXN2 gene." (PMID 20016785, 2009). "We sequenced the 25 coding exons of the human ATXN2 gene in 92 severely obese children enrolled in the Genetics of Obesity Study (GOOS) with a mean body mass index >3.2 standard deviations above the mean." (PMID 20016785, 2009). "We previously generated ataxin-2 (Atxn2) knockout mice and demonstrated that these animals lacked obvious anatomical abnormalities of the CNS, but showed marked obesity and reduced fertility." (PMID 19617910, 2009). "This dosage sensitivity suggests the ATXN2 gene as a good candidate for detailed analysis of genetic variation, both common and rare, in a number of human phenotypes as diverse as obesity, motor hyperactivity, anxiety, and depression." (PMID 19617910, 2009).
Obesity (continued). "Knock-out of the ATXN2 gene in the mouse resulted in marked obesity with onset shortly after weaning." (PMID 20016785, 2009). "To elucidate a potential role for ATXN2 in human obesity we examined the coding region of ATXN2 in 92 patients with severe obesity of early onset recruited to the UK Genetics of Obesity Study." (PMID 20016785, 2009). "We sequenced the 25 coding exons and intron-exon boundaries of ATXN2 in children with severe obesity." (PMID 20016785, 2009). "ATXN2 deletions can lead to insulin resistance and obesity in mice." (PMID 34899825, 2021). "Ataxin-2 knockout mice exhibit progressive obesity, dyslipidemia, and insulin resistance." (PMID 31766565, 2019). "ATXN2 deficiency in the rodent did not result in a neurodegenerative phenotype, but led to marked obesity." (PMID 20016785, 2009). "The genetic deletion of ataxin-2 orthologs rescues the lethality of poly(A)-binding-protein-KO in yeast, triggers phenotypes of large cell size and fat accumulation in nematodes, produces female sterility in flies, and results in obesity, insulin resistance, hyperlipidemia, and infertility in mice." (PMID 31766565, 2019). "Specifically, interactions between miR-130b-3p/ATXN2, and miR-142-5p/NAMPT may play important roles in regulation of host metabolism, given that loss of function mutations in both ATXN2 and NAMPT are associated with obesity and diabetes mellitus." (PMID 30020932, 2018). "Taken together, these disease-focused studies reveal putative roles for ATXN2 in processes that are deregulated in several diseases including PD, SCA1, MJD, tauopathies, POAG and obesity/type I diabetes." (PMID 28587229, 2017). "The ATXN2‐knockout mice exhibit no significant neurological problems, except obesity with insulin resistance and dyslipidemia, suggesting that ATXN2 plays a minor role in the nervous system." (PMID 39473221, 2024). "Atxn2 plays a role in the metabolism of branched-chain and other amino acids, metabolism of fatty acids, and in the citric acid cycle, with mice lacking Atxn2 demonstrating sensitivity to diet-induced obesity." (PMID 33242659, 2021). "The genetic ablation of Atxn2 in mice does not lead to a neurodegenerative process with weight loss such as SCA2, but instead to obesity, lipid anomalies, and insulin resistance." (PMID 26868665, 2017). "On the other hand, mice lacking Atxn2 exhibit obesity as a consequence of insulin resistance and altered lipid metabolism pathways." (PMID 25902068, 2015). "ATXN2 is also important in energy metabolism and weight regulation, as mice lacking Atxn2, developed obesity and insulin resistance." (PMID 25902068, 2015). "However, in our hands, the knockdown of Atx2 resulted in flies that ate less, and mice without Atxn2 show a phenotype of adult-onset obesity." (PMID 33242659, 2021).
Huntington disease (13 papers, 2007 to 2025). Huntington disease (HD) is a rare neurodegenerative disorder of the central nervous system characterized by unwanted choreatic movements, behavioral and psychiatric disturbances and dementia. "In a Drosophila model of Huntington's disease, the cIDR of ATXN2 has been found to promote Huntington's protein aggregation and neurodegeneration, indicating its essential role in protein inclusion body formation." (PMID 39039334, 2024). "While researchers have proposed three broad mechanisms to explain these observations, further studies are needed to fully elucidate the role of ATXN2 in Huntington's disease." (PMID 39039334, 2024). "A more recent study of Huntington’s disease (HD) in Drosophila showed a connection between polyQ expanded Huntingtin (Htt) and Ataxin-2." (PMID 34718534, 2021). "SCA2 is caused by a CAG triplet repeat expansion in the ATXN2 gene and, therefore, belongs to the group of CAG triplet repeat disorders like SCA1, SCA3, SCA6, SCA7, SCA17, Huntington’s Disease (HD), Dentatorubral pallidoluysian atrophy (DRPLA), and Spinal and bulbar muscle atrophy (SBMA)." (PMID 26868665, 2017). "PolyQ-expanded Ataxin-2 abundance in biofluids would be an obvious candidate biomarker for SCA2, similar to what was described for huntingtin or Ataxin-3 proteins in Huntington ́s disease (HD) or SCA3, respectively." (PMID 41298695, 2025).
type 1 diabetes (10 papers, 2011 to 2025). "This variant is associated with susceptibility to several autoimmune diseases, including celiac disease, type 1 diabetes, vitiligo, and rheumatoid arthritis, suggesting more relevance for TPOAb levels than ATXN2." (PMID 24586183, 2014). "This region, which encompasses ATXN2 and SH2B3 genes, has been previously associated with several complex diseases, such as retinal vascular caliber and chronic kidney disease, myocardial infarction or type 1 diabetes." (PMID 23844121, 2013).
diabetes mellitus (9 papers, 2015 to 2025). A metabolic disorder characterized by abnormally high blood sugar levels due to diminished production of insulin or insulin resistance/desensitization. "ATXN2 is a pleiotropic gene linked to various diseases, including diabetes and inflammation." (PMID 35784282, 2022). "Similarly, both ATXN2 and HECTD4 are associated with diabetes mellitus, and we identified known MI regions uniquely associated with single MI in these genes." (PMID 38725839, 2024). "Studies demonstrated that an ATXN2 KO mouse model is associated with a metabolic syndrome, involving hypercholesterolemia and diabetes mellitus, possibly related with a post-transcriptional effect of ATXN2 on the insulin receptor expression in liver and in cerebellum." (PMID 37845370, 2023).
glaucoma (9 papers, 2019 to 2025). Increased pressure in the eyeball due to obstruction of the outflow of aqueous humor. "Recent studies have linked high IOP in primary open-angle glaucoma (POAG) to single nucleotide polymorphisms in the ATXN2 gene." (PMID 39039334, 2024). "TBK1, OPTN, and ATXN2 variants all cause familial ALS but also glaucoma." (PMID 38658168, 2024). "However, more research is needed to fully understand the molecular mechanisms underlying the involvement of ATXN2 and the other potential genes/genomic loci in body fat control and glaucoma." (PMID 36835334, 2023). "Another ALS-associated protein, ATXN2, has also been associated with primary open-angle glaucoma." (PMID 36099048, 2022). "In addition to its role in glaucoma, ATXN2 has been linked to body fat regulation." (PMID 36835334, 2023). "Replicated associations included for instance that between rs10774625 (nearest gene: SH2B3/ATXN2) and coeliac disease, and that between rs12350420 (nearest gene: MVB12B) and glaucoma." (PMID 40493586, 2025).
Insulin resistance (9 papers, 2009 to 2024). Increased resistance towards insulin, that is, diminished effectiveness of insulin in reducing blood glucose levels. "However, instead of a neurodegenerative phenotype, ATXN2-deficient rodents exhibited phenotypes characterized by abdominal obesity, insulin resistance, and marked hepatosteatosis (i.e. lipid accumulation in the liver)." (PMID 22022282, 2011).
Hypertension (8 papers, 2013 to 2024). The presence of chronic increased pressure in the systemic arterial system. "Examining the associations between individual urate genetic risk loci and the related disease outcomes highlighted two loci, GCKR and PTPN11/ATXN2, which drive their association with hypercholesterolemia, hypertension, and ischemic heart disease." (PMID 31626644, 2019). "Interestingly, both SH2B3 and ATXN2 genes have also been associated with cardiovascular alterations, such as myocardial infarction, hypertension, blood pressure and retinal vascular caliber." (PMID 23844121, 2013). "For PC1, shared genetic variants with diastolic blood pressure (ATXN2, GOSR2, NOS3, BAG3) and hypertension (ATXN2, VEGFB, NOS3, BAG3) were also observed." (PMID 39543113, 2024).
Machado-Joseph disease (8 papers, 2012 to 2025). "In a transgenic mouse model of Machado-Joseph disease, the decrease in ATXN2 levels may cause translational dysregulation by releasing PABP from overly active protein translation." (PMID 39039334, 2024). "Another group identified a 9-base pair duplication in the 2-gene ATXN2 sense/antisense region, which can decrease the age at onset for both spinocerebellar ataxia 3 (SCA3) and C9ORF72-ALS." (PMID 37250416, 2023). "Studies have shown that in patients and animal models with Machado-Joseph disease, ATXN2 levels are reduced, while the accumulation of ATXN3MUT drives ATXN2 from the cytoplasm into the nucleus." (PMID 39039334, 2024). "The most frequent SCA worldwide are those caused by CAG repeat expansions, as SCA1 (in ATXN1), DRPLA (ATN1), SCA2 (ATXN2), Machado-Joseph disease (MJD)/ SCA3 (ATXN3), SCA6 (CACNA1A), SCA7 (ATXN7), and SCA17 (TBP), usually designated polyglutamine (polyQ) ataxias." (PMID 39048885, 2024).
motor neuron disease (8 papers, 2011 to 2021). "An increased risk for motor neuron disease was reported in intermediate alleles of ATXN2 gene." (PMID 33673860, 2021). "SG component proteins with a causal role for motor neuron diseases include TDP-43 (gene symbol TARDBP), FUS, ATXN2, SMN, Tau (gene symbol MAPT), HNRNPA2B1, and HNRNPA1." (PMID 24659297, 2014). "Mutations in RNA binding proteins such as Tar DNA binding protein-43 (TDP-43), Fused in sarcoma (FUS), survival of motor neuron (SMN1), ataxin-2 (ATX2), optineurin (OPT) and angiogenenin (ANG) all cause motor neuron diseases." (PMID 23164372, 2012). "Our study establishes the importance of ATXN2 in motor neuron disease and SCA2 mouse models." (PMID 32307524, 2020). "Increasing number of evidences found that ATXN2 gene plays key role in neural diseases like dementia and motor neuron disease which could affect cognitive function." (PMID 30349449, 2018). "It was recently demonstrated that the downregulation of Ataxin-2, a lipid-storage factor and mTOR-repressor upstream from PINK1, may postpone death in a mouse model of motor neuron disease from 20 to over 300 days." (PMID 28768533, 2017).
rheumatoid arthritis (8 papers, 2014 to 2025). A chronic, systemic autoimmune disorder characterized by inflammation in the synovial membranes and articular surfaces. "Examples include the association of the APOE/TOMM40 locus with pancreatic cancer and total cholesterol levels, the association of the ABO locus with macular degeneration and coronary artery disease, and the association of the SH2B3/ATXN2 locus with diastolic blood pressure and rheumatoid arthritis." (PMID 26677855, 2015). "Other loci containing alleles robustly associated with higher eosinophil count and increased risk of rheumatoid arthritis were COG6, SPRED2, RUNX1, and the highly pleiotropic ATXN2/SH2B3/BRAP region." (PMID 27863252, 2016).